MDM4 (MDM4 regulator of p53)
Diseases named in the same sentence as MDM4 in open-access papers (continued):
Sharing a sentence is not in itself a finding about the gene and the disease.
cancer (continued). "Moreover, SNHG12 was also reported to be involved in the tumorigenesis of other cancers by interacting with miR-129-5p/WWP1, miR-195/CCNE1, miR-125-5p/MDM4, miR-326/E2F1, and miR-15a-5p/SALL4 axes." (PMID 33294456, 2020). "In human cancers, an increasing expression of MDM4 is promoted by a non-sense-mediated, decay-targeted isoform of MDM4 (MDM4-S) by enhancing exon 6 inclusion." (PMID 33072610, 2020). "MDM4, also known as MDMX, is an important player in cancer progression." (PMID 31217907, 2019).
cancer (continued). "Similarly, RBM47-induced splicing changes were seen in genes such as SLK, MDM4 and TNC, all of which are genes with known functions in cancer." (PMID 24898756, 2014). "The specific mechanism may be related to the cancer-related protein MDM4, but it is not-well defined." (PMID 38800376, 2024). "Although the development of MDM4 inhibitors lagged behind that of MDM2 inhibitors, it has been increasingly promoted in recent years, in part by research showing that the persistent expression of MDM4 in cancer cells counteracted the cytotoxic effects of MDM2 inhibition." (PMID 37686602, 2023). "Moreover, even if MDM2 rs3730485 and MDM4 rs4245739 were studied in several types of cancer, none of them included AML patients." (PMID 32492903, 2020). "Despite the emerging role of MDM4 (structural homologue of MDM2) in the pathogenesis, maintenance, and chemo-resistance of human cancer, there are currently no selective MDM4 antagonists undergoing clinical trial evaluation." (PMID 26095524, 2015). "Interestingly, our RNA-Seq data showed that MRPS31P5, MDM4 and THBD were expressed at significantly higher levels only in cancer tissues, while PCNXL3 did not result to be differentially expressed." (PMID 32992457, 2020).
cancer (continued). "We note this narrower CNA segment does not include the MDM4 oncogene, which is located at 1q32.1, thus other genes must be driving this recurrent genetic change in CNA-PC86, with possible candidates being known cancer genes BCL9 (1q21.2), ARNT (1q21.3), SETDB1 (1q21.3), or SF3B4 (1q21.2)." (PMID 41023738, 2025). "Hence we suggest that the ubiquitination of MDM4 may lead to the growth arrest of LADC, allowing cancer cells to maintain in early stage, not to progress to middle stage LADC." (PMID 31217907, 2019).
tumor (293 papers, 2008 to 2026). "Other variants such as MDM4-A and MDM4-211 have also been associated with tumor development and progression, but the exact role(s) remain incompletely understood." (PMID 39960347, 2025). "An elevated MDM4 expression associated with 1q gain indicates a possible role of MDM4 inhibitor for these neoplasms which needs to be tested in the clinical setting in the future." (PMID 39715854, 2025). "We found that MDM4 overexpression is often accompanied by adverse clinical features, poor prognosis, oncogenic mutations, tumor-immune infiltration and aberrant activation of oncogenic signaling pathways." (PMID 38281029, 2024). "We also investigated the correlations between MDM4 expression and prognostic value, immune features, genetic mutation, and tumor-related pathways." (PMID 38281029, 2024). "A recent study also characterized the association of MDM4 isoforms with tumor progression and outcome." (PMID 39273363, 2024). "The authors evidenced the association of the A allele of a novel MDM4 SNP (rs4252707) with the increased risk of this tumor." (PMID 34307167, 2021). "MDM2 rs2279744 (MDM2 309T>G) and rs3730485 (MDM2 del1518) and MDM4 rs4245739 (MDM4 34091 C>A) variants were reported to influence the genes activity being associated with carcinogenesis and tumor progression." (PMID 32492903, 2020). "Nonetheless, the expression of splice variant of Mdm4 and one other gene was clearly evident in a range of mouse tumor samples." (PMID 28460439, 2017). "There is also evidence that over-expression of MDM4 was associated with not only tumor progression but also worse prognosis." (PMID 28099948, 2017). "To date, this is the first study to explore the association of MDM4 polymorphisms with tumor HPV16 status in SCCOP." (PMID 29156829, 2017). "In particular, multiple studies show that expression of a splice variant of MDM4, MDM4-S correlates with tumor aggressiveness and can be used as a prognostic marker in different tumor types." (PMID 28460439, 2017). "MDM4 expression occurs when tumor cells have acquired MDM4 amplification, activated KRAS mutations, or loss of miR-34a-mediated suppression." (PMID 25621298, 2014). "It is possible that these differences between the genotype of MDM2 SNP309 and MDM4 SNP7 are due to copy number changes of MDM2 or MDM4 in the tumor sample that result in overrepresentation of one allele in the tumor sample." (PMID 22916154, 2012). "Analysis of the association of MDM4 variant expression with tumor properties has evidenced some significant correlations." (PMID 19721810, 2009). "Coimmunoprecipitation experiments in tumor cell lines have shown the association between endogenous proteins MDM4 and pRB." (PMID 19721810, 2009).
tumor (continued). "Molecular analysis of the HCC-like component of the tumor, demonstrated a highly unstable hyperdiploid genome and evidence of altered cell cycle control, possibly associated with the MDM4 copy gain (located in 1q32), as well as MAPK signaling pathway activation resulting from the RPS6KA3 variant." (PMID 37903123, 2024). "Finally, we carried out some in vitro experiments including colony formation assay, chemoresistance and senescence-associated β-galactosidase activity assay to study the anti-tumor treatment effect of small molecule MDM4 inhibitor, NSC146109." (PMID 38281029, 2024). "MDM4 overexpression has been associated with tumor formation and a poorer prognosis." (PMID 36624687, 2023). "Multiple SNPs within the MDM4 locus have been correlated to increased tumor risk." (PMID 34065345, 2021). "Therefore, we performed an analysis of Mdm4 expression in RCC tumor tissues versus in normal tissues as well as a survival association analysis of the RCC patients with high Mdm4 expression version with low Mdm4 expression." (PMID 34384473, 2021). "In conclusion, our present study provides evidence for the first time that three MDM4 gene polymorphisms could significantly modify individually or in combination the tumor HPV status in SCCOP." (PMID 29156829, 2017). "Accordingly, several in vivo studies underlined the addiction of various tumor cells to MDM4." (PMID 28230750, 2017). "Some studies have indicated the development of SCCOP associated with HPV16 may be affected by MDM4 genetic variants, while whether MDM4 variants are associated with tumor HPV16 status in SCCOP patients remains unknown." (PMID 29156829, 2017). "Our study demonstrated that some genetic variants of MDM4 may individually or jointly modify tumor HPV16 status in SCCOP." (PMID 29156829, 2017). "Three MDM4 variant genotypes were significantly associated with HPV16 tumor status among SCCOP patients compared with the common homozygous genotypes (OR, 0.6; 95% CI, 0.4–1.0 for rs10900598; OR, 1.6, 95% CI; 1.1–2.4 for rs1380576; and OR, 1.8, 95% CI, 1.1–2.9 for rs11801299; respectively)." (PMID 29156829, 2017). "MDM4 genetic variants could be biomarkers for predicting tumor HPV16-positivity of patients with SCCOP, particularly in never-smokers and never-drinkers SCCOP patients." (PMID 29156829, 2017). "Recent studies suggest that expression of splice variants of Mdm2 and Mdm4 may be similarly involved in tumor development." (PMID 28460439, 2017). "Our results indicate that the combination of variant genotypes of the 3 MDM4 variants may be use to serve as more valuable markers for the HPV tumor status of SCCOP." (PMID 29156829, 2017). "Overexpression of MDM4 is associated with tumor progression and poor prognosis." (PMID 27687591, 2016). "Thus, given the role of HPV16 status as a biomarker for predicting prognosis of SCCOP, we evaluated whether MDM4 polymorphisms could be served as a susceptibility biomarker for HPV16 tumor status in SCCOP patients." (PMID 29156829, 2017).